TACC3 (transforming acidic coiled-coil containing protein 3)
Diseases named in the same sentence as TACC3 in open-access papers (continued):
Sharing a sentence is not in itself a finding about the gene and the disease.
cancer (continued). "As TACC3 shows frequent mutations in many cancers and induces cancer transformation, the results of this study may provide molecular basis of the cancer promoting activity of TACC3." (PMID 31823729, 2019). "Transforming acidic coiled-coil protein 3 (TACC3) is a cancer-associated protein that binds ch-TOG." (PMID 25596274, 2015). "In any case, it is clear that TACC3 deregulation is associated with cancer." (PMID 26682275, 2015). "It has been suspected that deregulation of TACC3 may be associated with the development of various types of human cancer." (PMID 25760075, 2015). "It has been suspected that deregulation (both up- and down-regulation) of TACC3 may be associated with the development of various types of human cancer." (PMID 23936413, 2013). "CA, a hallmark of aggressive cancers, involves TACC3 forming a complex with integrin-linked kinase and chTOG at the centrosomes of CA cancer cells." (PMID 39603208, 2025). "High expression of TACC3 may be associated with some human cancers." (PMID 38012214, 2023). "In this study, we identified TACC3 as being strongly upregulated in cancers with CA and associated with worse clinical outcome in highly aggressive patient subpopulations, especially in TNBC." (PMID 36864125, 2023). "Targeting TACC3 with inhibitors can induce mitotic catastrophe and G1 phase arrest, leading to cancer cell death, making it a promising therapeutic target for aggressive cancers." (PMID 40791849, 2025). "Further analysis of multiple independent HCC datasets revealed that TACC3 mRNA was markedly upregulated in cancer tissues compared with peritumoral samples." (PMID 40866361, 2025). "TACC3 is overexpressed in a variety of cancers and therefore represents a therapeutic target for the treatment of the respective malignancies." (PMID 40585227, 2025). "Transforming acidic coiled-coil protein-3 (TACC3) has been identified as a critical factor in tumor progression and immune infiltration across cancers, including NSCLC." (PMID 39603208, 2025). "Although emerging evidence highlights the strong prognostic value of elevated TACC3 expression across various cancers and its potential as a therapeutic target, the molecular mechanisms driving TACC3 upregulation remain poorly understood." (PMID 40246827, 2025). "The development of this novel probe disrupting the TACC3/CHC interface in a cellular context highlights the significance of this interface as a potential cancer therapeutic target." (PMID 40585227, 2025). "TACC3 is a centrosomal protein that regulates the stability of the mitotic spindle, and its dysregulation is related to chromosomal instability in cancer." (PMID 41194971, 2025). "Abnormalities of the TACC3 protein resulting from rearrangements have been shown to result into aneuploidy, chromosomal segregation errors, and cancer progression." (PMID 39387893, 2025). "Given the therapeutic relevance of metabolic reprogramming in cancer, we focused on elucidating TACC3’s impact on glycolytic metabolism." (PMID 40246827, 2025). "TACC3 and ch-TOG have previously been shown to be involved in centrosome clustering in cancer cells, either via interaction with integrin-linked kinase or with KIFC1." (PMID 40105698, 2025). "In the head and neck, only limited studies are available on the prevalence and clinicopathological characteristics of carcinomas harboring FGFR3::TACC3 fusions." (PMID 39387893, 2025). "Recognition of more cases is mandatory to verify the existence of a distinctive FGFR3::TACC3-driven carcinoma type and to address the role of targeted therapy in these poorly characterized tumors." (PMID 39387893, 2025).
cancer (continued). "Rearrangements represent approximately 10% of all FGFR alterations in cancer, with transforming acidic coiled coil containing the protein 3 (TACC3) being the most frequent fusion partner." (PMID 38730596, 2024). "Recently, TACC3 has attracted increasing research interest because it was found aberrantly expressed in cancers." (PMID 38757931, 2024). "Most FGFR3 fusions are with TACC3 as the gene partner and have been described in several types of cancers including GBM." (PMID 39590169, 2024). "These preclinical findings as well as the supporting clinical data strongly encourage the clinical testing of TACC3 inhibitors to improve the outcome of highly aggressive cancer patients bearing amplified centrosomes." (PMID 36864125, 2023). "This study further suggests the TACC3 dimerization domain of FGFR3-TACC3 as a novel target in treating FGFR translocation driven cancers." (PMID 36780330, 2023). "The TACC3-ch-TOG complex clusters supernumerary centrosomes in cancer cells in an ILK-and Aurora-A-dependent manner." (PMID 37508338, 2023). "To demonstrate the direct effects of TACC3 on mitotic progression, potentially specific to cancer cells with CA, we synchronized JIMT-1 and MCF-7 cells at mitosis using nocodazole, followed by release into fresh or BO-264-containing media." (PMID 36864125, 2023). "Despite the growing body of evidence showing strong prognostic value of TACC3 in cancer and a therapeutic potential for targeting TACC3 to inhibit tumor growth, little is known about the molecular mechanisms of TACC3-driven tumor growth." (PMID 36864125, 2023). "This suggests that loss of TACC3 interaction with the NuRD complex, and thus the transcriptional activation of tumor suppressors is involved in G1 arrest-mediated apoptosis under TACC3 inhibition in cancer cells with CA." (PMID 36864125, 2023). "TACC3 is currently an important molecular marker for cancer diagnosis and prognostic prediction, but the specific mechanism and role of TACC3 in tumorigenesis remain to be further elucidated." (PMID 38012214, 2023). "Overexpression of TACC3 at both the protein and mRNA levels has been observed in more than 40 types of cancers." (PMID 35855850, 2022). "The TACC3 protein interaction network was constructed using the GeneMANIA online tool to explore the role of TACC3 in the occurrence and development of cancer." (PMID 35855850, 2022). "The correlation between TACC3 and tumor mutational burden (TMB) and microsatellite instability (MSI) also demonstrated that TACC3 is closely related to TME in human cancers." (PMID 35855850, 2022). "TACC3 was found to be overexpressed in a variety of human cancers, including ovarian cancer, breast cancer, squamous cell carcinoma, and lymphoma." (PMID 35589670, 2022). "To understand the main cell types that express the TACC3 in cancer microenvironments, we performed the single-cell analysis of TACC3 in 78 single-cell datasets of cancer samples." (PMID 35855850, 2022). "It has been documented that TACC3 played a critical oncogenic role in various cancers and was required for cancer stem cells self-renewal." (PMID 35628623, 2022). "Owing to the limited current knowledge regarding the function of TACC3 in cancers, we intended to scrutinize its biological roles in LUAD and divulge its related regulatory pathways through conducting an all-inclusive analysis of open-access datasets." (PMID 35855850, 2022).
cancer (continued). "Stathmin1 and transforming acidic coiled-coil-containing protein 3 (TACC3) are two microtubule binding factors that are highly expressed in cancer cells and that maintain the stability of microtubules." (PMID 36221072, 2022). "We first assessed the relationship between TACC3 overexpression and patient prognosis in various types of cancers." (PMID 33714201, 2021). "Findings from an increasing number of studies provide possible mechanistic explanations for the relationship between high TACC3 expression and poor prognosis in various cancer types." (PMID 33714201, 2021). "Accumulating evidences indicate that transforming acidic coiled-coil 3 (TACC3) is a tumor-related gene, was highly expressed in a variety of human cancers, which is involved in cancer development." (PMID 34149795, 2021). "Because tumor-infiltrating lymphocytes correlate with improved prognosis in many cancers, we determined the levels of immune cell infiltrating in low and high TACC3-expressing tissues using data from TCGA." (PMID 33714201, 2021). "A great deal of effort has been expended on studying the biological mechanisms of TACC3 over-expression in cancers." (PMID 34149795, 2021). "As shown in the pan-cancer view, the 4 hub genes (IFI16, LMNB1, RHBDF2, and TACC3) were significantly up-regulated in ccRCC samples and other cancer types when compared to adjacent normal tissues (p < 0.001)." (PMID 33796525, 2021). "A recent study showed that FGFR3/TACC3 fusion leads to excessive mitochondrial movement, which provides energy for rapid cell growth, thereby supporting cancer development." (PMID 30999937, 2019). "Alteration of TACC3 expression levels has been found in many cancer types and leads to chromosomal segregation errors." (PMID 30344944, 2018). "Conversely, ectopic expression of TACC3 enhanced proliferation and growth in cancer cells compared with control cells according to MTT assays and foci-formation assay." (PMID 29358577, 2018). "Overexpression of TACC3 has been shown in a variety of human cancers, and correlated with lower survival rate and tumorigenesis." (PMID 29520231, 2018). "Accumulating evidence has shown that transforming acidic coiled-coil 3 (TACC3) is deregulated in a broad spectrum of cancers." (PMID 29358577, 2018). "Multiple roles for TACC3 in cancer progression have been described: high levels of TACC3 can lead to accumulation of DNA double-strand breaks and disrupt normal DNA damage pathways and proper chromosome segregation." (PMID 27956147, 2017). "Recent studies indicated that paclitaxel, a microtubule-interfering cancer drug, diminished TACC3 transcription in a time- and dose-dependent manner, providing an alternative modality for TACC3 intervention." (PMID 28273854, 2017). "The pooled data showed that increased TACC3 expression was positively associated with advanced clinical stage, lymph node metastasis and tumor differentiation, which indicated that upregulated TACC3 might have a significant relationship with advanced features of cancer." (PMID 29088887, 2017). "TACC3-induced EMT empowered cancer cells with the abilities to invade, to resist apoptosis and to disseminate." (PMID 28273854, 2017). "Though many studies have tried to explore how TACC3 plays a role in cancer progression, its potential molecular mechanisms of cancer progression remained unclear." (PMID 29088887, 2017). "Transforming acidic coiled-coil-containing protein 3 (TACC3), a microtubule regulator, is associated with various cancers." (PMID 29135996, 2017). "Further, a plenty of studies have showed that TACC3 overexpression was highly correlated with low survival rate in cancer patients." (PMID 29088887, 2017). "Our analysis suggested TACC3 overexpression had a positive correlation with the worse overall survival in cancer patients." (PMID 29088887, 2017).
cancer (continued). "Abnormality of microtubules/centrosomes causes mitotic spindle defects and correlates with tumorigenesis and tumor progression; therefore, the involvement of TACC3 in various cancers has been reported." (PMID 29135996, 2017). "If the mitotic defects observed in FT3-positive cancer cells are due to reduced TACC3 level on the mitotic spindle, then increasing the level of TACC3 by overexpression in these cells should rescue the defects." (PMID 28855393, 2017). "Our studies reveals that there was a significant relationship between TACC3 overexpression and poor prognosis in cancer patients." (PMID 29088887, 2017). "Recent studies have showed that the transforming acidic coiled coil 3 (TACC3), was aberrantly up-regulated in various solid tumors and was reported to be correlated with unfavorable prognosis in cancer patients." (PMID 29088887, 2017). "Even though simple comparison is difficult due to the heterogeneity of STS, it is possible that, in STS, TACC3 is involved in the tumor differentiation as with other malignant tumors." (PMID 29135996, 2017). "The referenced studies have revealed that TACC3 mainly promotes tumour progression by enhancing cell proliferation, cancer stem cell populations and cancer cell migration." (PMID 27248823, 2016). "Accumulating evidence indicates that alterations in TACC3 expression depend on the organ and type of cancer." (PMID 27705912, 2016). "In several types of tumours, a common TACC3 fusion gene known as FGFR3-TAAC3 has been shown to promote the development of cancer cells by promoting cell proliferation." (PMID 27248823, 2016). "Transforming acidic coiled-coil protein-3 (TACC3), a frequently aberrantly expressed oncogene, is an important biomarker in various human cancers." (PMID 27248823, 2016). "As the emerging importance of TACC3 for cancer is increasingly apparent, we are better positioned to strategically address knowledge gaps in cancer etiology, and more effectively reap the harvest of personalized cancer therapy." (PMID 26682275, 2015). "TACC3 levels in various cancers are controversial and are correlated with the type of cell, organ or carcinoma, and the molecular mechanisms of TACC3 remain elusive." (PMID 26219398, 2015). "Given these associations, it is imperative to clarify the precise mechanistic contribution of TACC3 to tumorigenesis and cancer development." (PMID 26682275, 2015). "Previous work explored the possibility that overexpression of TACC3 increases cell invasiveness and promotes a more aggressive cancer phenotype." (PMID 25596274, 2015). "While knowledge gaps of TACC3's role in cancer still remain, the clinical-translational significance of TACC3 is becoming increasingly clear." (PMID 26682275, 2015). "Intriguingly, SNIPER(TACC3) selectively induced cell death in cancer cells expressing a larger amount of TACC3 protein than normal cells." (PMID 25375378, 2014). "We also show that cancer cells expressing a large amount of the TACC3 protein readily undergo cell death as the result of SNIPER(TACC3) treatment." (PMID 25375378, 2014). "One of the interesting feature of SNIPER(TACC3) is the ability to induce apoptosis selectively in cancer cells expressing large amounts of TACC3 protein." (PMID 25375378, 2014). "SNIPER(TACC3) at ≥10 μM efficiently killed the cancer cells, which is consistent with the protein knockdown activity under long-term (24 h) treatment." (PMID 25375378, 2014). "We also examined the effects of SNIPER(TACC3) on the viability of other cancer cell lines and normal cells." (PMID 25375378, 2014). "TACC3 has a conserved function to promote centrosomal microtubule assembly, a process which is often altered in cancer cells." (PMID 21113414, 2010). "Notably, the FGFR3::TACC3 fusion plays a role in tumorigenesis in various cancers, including bladder, lung, and uterine cervical malignancies, underscoring its broader oncogenic significance." (PMID 40417325, 2025).
cancer (continued). "Notably, TACC3 expression correlates with CC score in the pan-cancer CCLE dataset with CA20 expression and the NCI60 cell line panel." (PMID 36864125, 2023). "Based on our novel findings, TACC3 inhibition may represent a novel way of inhibiting NuRD complex in cancer." (PMID 36864125, 2023). "Along these lines, TACC3 may represent an excellent drug target with a strong translational potential in the treatment of highly aggressive cancers as 1)." (PMID 36864125, 2023). "We demonstrated that TACC3 is not only a key regulator of clustering centrosomes and mitotic progression, but also controls G1/S transition via forming distinct functional interactomes during cell cycle progression in cancer cells with CA." (PMID 36864125, 2023). "Indeed, even if TACC3 is by far the most common (>80% of cases) gene partner in FGFR3 rearrangements in cancer, several other partner genes have been detected." (PMID 38067258, 2023). "We showed, for the first time, that TACC3 forms distinct functional interactomes during cell cycle progression (both mitosis and interphase) that are essential for the proliferation and survival of cancer cells with CA." (PMID 36864125, 2023). "To test whether TACC3 may have novel functions beyond mitosis to promote cell cycle progression in cancer cells with CA, we synchronized JIMT-1 cells at G1 using double thymidine block, followed by release into fresh or BO-264 containing media." (PMID 36864125, 2023). "Interestingly, targeting TACC3 proved a viable strategy in TACC3-overexpressing cancers, likely by inducing abundant multipolar spindles, which led to mitotic arrest and apoptosis." (PMID 34207779, 2021). "Based on these studies, it seems that TACC3 may promote tumor progression by increasing cell proliferation, cancer stem cell population, and cancer cell migration." (PMID 34149795, 2021). "TACC3 is a tumor-related gene related to cancer development." (PMID 34149795, 2021). "ECA samples showed increased TACC3 expression relative to adjacent non-carcinoma samples." (PMID 34134633, 2021). "Moreover, TACC3 is commonly overexpressed in cancers and positively correlated with poor overall survival and disease-free survival." (PMID 33362856, 2020). "TACC3 inhibitor could reduce sphere formation, clonogenicity, cell growth and proliferation, and cancer stem cell-like phenotype by suppressing the Wnt/β-catenin and PI3K/AKT signaling pathways." (PMID 33362856, 2020). "To prevent and overcome this problem, we focused on both fused genes FGFR3 and TACC3 in FGFR3-TACC3 fusion-positive cancer because the kinase fusion protein may have not only kinase action but also other actions based on the non-kinase fused gene." (PMID 29358619, 2018). "Based on those studies, it appears TACC3 may promote tumor progression by increasing cell proliferation, cancer stem cell populations, and cancer cell migration." (PMID 30341253, 2018). "Taken together, TACC3 could serve as a promising biomarker for monitoring the progression of malignancies and represent a new target for the treatment of cancers." (PMID 29088887, 2017). "It suggested that TACC3 could be an potential independent prognostic factor for predicting OS of cancer patients." (PMID 29088887, 2017). "Via changing key cell processes, initiating oncogenic signal transduction pathways and inducing genomic instability, the up- and downregulation of TACC3 may promote the development of cancers." (PMID 29088887, 2017). "Most studies studies have demonstrated that TACC3 expression was upregulated in many cancers." (PMID 29088887, 2017).